OGT (O-linked N-acetylglucosamine (GlcNAc) transferase)
Diseases named in the same sentence as OGT in open-access papers (continued):
Sharing a sentence is not in itself a finding about the gene and the disease.
prostate carcinoma (continued). "In addition, they examined OGT expression using the OncomineTM Database and found elevated OGT mRNA expression patterns in human prostate carcinoma compared with normal adjacent tissue in more than 200 patient samples." (PMID 24918087, 2014). "Furthermore, studies indicate that OSMI-1, either alone or combined with doxorubicin, was effective in decreasing OGT enzyme levels and increasing apoptosis in prostate cancer cells, presenting a potential alternative treatment strategy for enhancing cancer therapy effectiveness." (PMID 39487556, 2024). "Similar results for OGT immunohistochemical overexpression relating to such clinical parameters as larger primary tumor size, positive nodal status, higher grade of malignancy according to Gleason scale and increased metastases incidence were also reported in another study of prostate cancer." (PMID 25315705, 2015). "We performed an unbiased combinatorial lethality screen, which revealed that combined inhibition of OGT and cyclin-dependent kinase 9 (CDK9) is selectively toxic to prostate cancer cells." (PMID 35164752, 2022). "Prostate cancer specific SNPs are bound by MRE11 and O-GlcNAc at different levels, which we propose to represent the temporal separation in the chromatin-arrival of OGT and MRE11 during DNA repair." (PMID 35164752, 2022). "The data generated using the Seahorse system showed that the ability of prostate cancer cells to generate ATP was severely compromised when both CDK9 and OGT were inhibited." (PMID 35708495, 2022). "In this study, we have employed a multiomics approach to understand how prostate cancer cells rewire transcriptional, proteomic, and metabolic networks when CDK9 and OGT are inhibited." (PMID 35708495, 2022). "The starting point for our study was the combinatorial lethality screen, which discovered that co-targeting of OGT and CDK9 is toxic to prostate cancer cells; our goal in this project was to understand why this is." (PMID 35708495, 2022). "By identifying the proteins that are increasingly O-GlcNAcylated in response to CDK9 inhibition, we can establish mechanistically, why combined inhibition of OGT and CDK9 is toxic to prostate cancer cells." (PMID 35164752, 2022). "We have shown that combined inhibition of OGT and CDK9 is toxic to prostate cancer cells, and here we used a multiomics approach to explain the mechanistic basis for the combinatorial effects." (PMID 35708495, 2022). "Co-targeting of O-GlcNAc transferase (OGT) and the transcriptional kinase cyclin-dependent kinase 9 (CDK9) is toxic to prostate cancer cells." (PMID 35708495, 2022). "Combined inhibition of CDK9 and OGT or MRE11 further decreases RNA polymerase II activity, induces DNA damage signaling, and blocks the survival of prostate cancer cells." (PMID 35164752, 2022). "Having established a dose of OGT inhibitor ST045849 for metabolic profiling, we used 1H NMR spectroscopy to analyse cell culture media of LNCaP prostate cancer cells treated with the OGT inhibitor." (PMID 26824323, 2016). "OGT O-GlcNAcylates thousands of proteins, and we use comprehensive glycoproteomic profiling to understand how depletion of CDK7 activity remodels OGT substrate repertoire in the CRPC cells and in the androgen-dependent prostate cancer cells." (PMID 36401094, 2023). "In prostate cancer specific SNPs, most of the loci are marked either by MRE11, O-GlcNAc or both, which likely represents the temporal separation in the chromatin-arrival of OGT and MRE11 during the DNA repair-process." (PMID 35164752, 2022). "We earlier performed a comprehensive screen to discover compounds that sensitize prostate cancer cells to OGT inhibitors, and this work led to the discovery of combinatorial lethal interaction between OGT and CDK9 inhibitors that is specific to prostate cancer cells." (PMID 35164752, 2022).
prostate carcinoma (continued). "We hypothesized that CDK9 inhibition affects O-GlcNAcylation of CDK9 because combined inhibition of OGT and CDK9 is toxic to prostate cancer cells, OGT inhibition decreases phosphorylation of CDK9 and CDK9 is known to be O-GlcNAcylated." (PMID 35164752, 2022). "Furthermore, the OGT inhibitor OSMI-2 decreases global chromatin O-GlcNAcylation and inhibits the proliferation of prostate cancer cells as a single drug." (PMID 33194731, 2020). "Indeed, reduced OGT results in a lower angiogenic potential and decreased vascular endothelial growth factor (VEGF) mRNA level in prostate cancer cell line." (PMID 33194731, 2020). "Both OGT and enzymes in the HBP pathway change in prostate cancer." (PMID 30893936, 2019). "We hypothesized that OGT activity is remodeled in response to CDK9 inhibitor treatment because combined inhibition of OGT and CDK9 is toxic to prostate cancer cells, OGT activity is remodeled in response to stress and OGT-dependent glycosylation alters protein function." (PMID 35164752, 2022). "Furthermore, in prostate carcinoma and bladder cancer cells, while the level of OGT/O-GlcNAcylation increased, the level of deglycosylase OGA decreased, prompting a dynamic imbalance between OGT and OGA." (PMID 33194731, 2020). "First, we confirmed that combined inhibition of OGT and CDK9 selectively inhibits proliferation of prostate cancer cells but does not have effects on normal prostate cells, as previously reported." (PMID 35164752, 2022). "In three prostate cancer cell lines (LNCaP, VCaP, and PC3), pharmacologically inhibition of OGT decreased MYC protein stability without affecting its mRNA levels." (PMID 23964270, 2013). "Interestingly, combinatorial targeting of OGT and CDK9 is selectively toxic to prostate cancer cells but not to normal prostate cells." (PMID 35708495, 2022).
Insulin resistance (29 papers, 2010 to 2025). Increased resistance towards insulin, that is, diminished effectiveness of insulin in reducing blood glucose levels. "By contrast, mutagenic loss of PTP1B’s OGT target sites rescued hyperlipidemia induced insulin resistance." (PMID 36111295, 2022). "Perturbations of OGA activity in cell culture, loss of OGA-1 activity in C. elegans, and OGT overexpression in mouse liver or fat promotes insulin resistance." (PMID 25505447, 2014). "However, in addition to cellular uptake proteins, HBP and/or OGT activity has been extensively linked to insulin resistance, particularly in adipose and skeletal muscle." (PMID 36111295, 2022). "Taking advantage of random X chromosome inactivation and mosaic OGT-deficiency in Foxp3YFP-Cre/wtOgtF/F female mice, we establish that functional deficiency in about half the Treg cells renders animals more prone to diet-induced adiposity and insulin resistance." (PMID 35874700, 2022). "OGT deletion also reduces circulating insulin levels and improves insulin resistance, glucose tolerance and insulin sensitivity; the liver is also improved by OGT deletion, as indicated by reduced lipid content." (PMID 41000247, 2025). "This was further confirmed when transgenic mice overexpressing human OGT in muscle and fat displayed higher O-GlcNAc levels and corresponding insulin resistance and hyperleptinemia." (PMID 39474868, 2024). "On the contrary, overexpression of adipose OGT inhibits fat breakdown in the adipose tissue and triggers diet-induced obesity, leading to whole-body insulin resistance." (PMID 38540730, 2024). "By contrast, the same studies show that under HFD conditions, adipose OGT OE (rat OGT knockin) worsens insulin resistance and Ogt KO (adiponectin-cre) prevents it altogether." (PMID 36111295, 2022). "Insulin resistance, facilitated by OGT depleted pro-inflammatory macrophages and adipose/liver hyper-O-GlcNAcylation, further impairs adipocyte FFA uptake and disinhibits FFA/VLDL secretion, adding back to circulatory hyperlipidemia." (PMID 36111295, 2022). "Treg cell-specific OGT deficiency renders mice more vulnerable to high-fat diet (HFD)-induced adiposity and insulin resistance." (PMID 35874700, 2022). "ogt-1 mutant worms have proven to be a powerful model of insulin resistance, stress, neurological disorders, and for identifying non-catalytic roles of OGT." (PMID 36383567, 2022). "When challenged with high fat diet, OGT ablation specifically in AgRP neurons exerted protective actions against diet-induced obesity and insulin resistance." (PMID 35527999, 2022). "The facilitative role of OGT in PTP1B-driven insulin resistance has been directly demonstrated in the liver." (PMID 36111295, 2022). "It was reported that OGT suppressed Insig-1, a negative regulator of lipid synthesis, and induced insulin resistance and dyslipidemia via PIP-dependent insulin signal disturbances." (PMID 35003298, 2021). "ITT and GTT showed that HFD-fed OGT AKI mice were less glucose-tolerant and less insulin-sensitive than WT control mice, demonstrating that OGT overexpression in adipose tissue promotes HFD-induced insulin resistance in mice." (PMID 31924761, 2020). "Together, these results show that adipocyte OGT drives diet-induced insulin resistance through obesity." (PMID 30504766, 2018). "Targeting OGT to the mouse liver led to significant insulin resistance and related metabolic defects through its interaction with phosphoinositides." (PMID 23326243, 2013). "In mammals, increasing O-GlcNAc levels by reducing O-GlcNAcase (OGA) activity or increasing O-GlcNAc transferase (OGT) activity leads to insulin resistance." (PMID 20952811, 2010). "The most compelling of these studies observed insulin resistance resulting from adenoviral-mediated overexpression of OGT in the liver or by transgenic overexpression of OGT in muscle and fat tissue." (PMID 20851344, 2010).
Insulin resistance (continued). "Earlier studies suggested that elevated O-GlcNAcylation levels resulting from increased expression of O-GlcNAc transferase (OGT) or inhibition of O-GlcNAcase (OGA) might contribute to insulin resistance through the hexosamine biosynthetic pathway (HBP)." (PMID 38540730, 2024). "Similarly, in the hypothalamus, agouti-related protein (AgRP) expressing neurons displayed enriched OGT, and selective knockout of this enzyme resulted in inhibition of neuronal excitability, protecting mice against insulin resistance and diet-induced obesity." (PMID 39474868, 2024). "Loss of OGT specifically in white adipocytes promoted lipolysis in visceral fat by decreasing O-GlcNAcylation, while adipose OGT overexpression diminished lipolysis in the adipose tissue and promoted diet-induced obesity, glucose intolerance and insulin resistance." (PMID 35527999, 2022). "When OGT is deficient in Treg cells, BAT insulin resistance and impaired thermogenesis could be observed, contributing to diet-induced obesity." (PMID 35874700, 2022). "OGT can also be recruited to the plasma membrane through the phosphoinositide-binding domain of OGT, which may induce insulin resistance." (PMID 36005597, 2022). "Similarly OGT overexpression or OGA inhibition has been shown to induce insulin resistance in various cell and animal models, and insulin sensitivity is improved via OGT KO in mice." (PMID 35173739, 2022). "Notably, OGT can participate in insulin resistance as a number of insulin signaling intermediates undergo O-GlcNAcylation." (PMID 33925229, 2021). "Together, these data show that adipocyte OGT deletion ameliorates diet-induced insulin resistance." (PMID 30504766, 2018). "OGT deletion decreased hyperinsulinemia, an insulin resistance index, and hyperleptinemia." (PMID 30504766, 2018). "Thus, consistent with results obtained with transgenic mouse models overexpressing OGT in muscles, these data suggest that OGT in skeletal muscle may promote insulin resistance, at least in part via downregulation of the expression of IL15." (PMID 36058931, 2022). "Interestingly, by investigating these mice on a longer period of time, they observed that the insulin resistance reversed 2–3 month after induction of the deletion, and that the mice surprisingly displayed increased insulin sensitivity 9.5 months after neuronal OGT-KO." (PMID 36058931, 2022). "In addition, we will discuss the common features that are shared between PHB and OGT, which may have implications in mediating sex differences in insulin resistance and metabolic dysregulation." (PMID 31118075, 2019). "Furthermore, transgenic mice overexpressing OGT show diabetic phenotype due to insulin resistance." (PMID 23056614, 2012). "Increased OGT in the liver has been reported to inhibit the expression of insulin signaling genes, such as IRS1 and Akt, contributing to insulin resistance." (PMID 36768465, 2023). "The role of HBP and protein O-GlcNAcylation in insulin resistance was clearly demonstrated by McClain (2002), who developed transgenic mouse models, which overexpress GFAT or OGT in different tissues." (PMID 34869586, 2021). "The samples from the carotid sheath showed an enriched expression of genes described to play a role in insulin resistance (PPP1R3E, PRKCQ, PRKCZ, CPT1B, MGEA5, RPS6KB2, OGT; KEGG_PATHWAY hsa04931:Insulin resistance)." (PMID 32661330, 2020). "On the other hand, OGT overexpression in adipose tissue inhibits stimulated lipolysis and promotes HFD-induced white fat accumulation and insulin resistance." (PMID 31924761, 2020). "Specifically, in our model, the OGTHetPl female mice may have had greater flexibility to increase or decrease OGT expression and subsequent O-GlcNAcylation flux which manifests as programmed protection from HFD-induced insulin resistance." (PMID 34203166, 2021).
Insulin resistance (continued). "Overexpression of OGT in the liver influences the phosphorylation of insulin-responsive proteins, namely, Akt and insulin receptor substrate 1 (IRS-1), which inhibits the kinase activity of Akt and induces the serine phosphorylation of IRS1, thus resulting in insulin resistance and dyslipidemia." (PMID 36768465, 2023). "Thus, while over-activation of O-GlcNAcylation in the liver leads to insulin resistance and promotes glucotoxicity, the absence of OGT can have deleterious effects, via an increase in cell death by apoptosis or necroptosis." (PMID 36058931, 2022). "In addition, mice lacking OGT in skeletal muscle were protected against HFD-induced insulin resistance." (PMID 35527999, 2022). "Consistent with this notion, transgenic animals overexpressing OGT or GFAT in the β cells of the pancreas, the liver, or in muscles and adipose tissue, develop phenotypes reminiscent of obesity or type 2 diabetes (hyperinsulinemia, hyperleptinemia, glucose intolerance, insulin resistance)." (PMID 36058931, 2022).
colon cancer (26 papers, 2014 to 2026). "High levels of OGT and its product, O-GlcNAcylation, were also reported in colon cancers and cancer cell lines and colitis-associated cancer patients but very few initiatives to measure the effect of OGT knockdown were conducted." (PMID 27252680, 2016). "Thus collectively, our results demonstrate that inhibition of GFAT or OGT combined with low-dose chemotherapy treatment induces a switch of colon cancer cells from senescence to apoptosis associated with an enhancement of DNA damage." (PMID 39426963, 2024). "Studies show that OGT and O-GlcNAcylation are significantly elevated in human colon cancer tissues and enhance the proliferation and migration of CRC cells." (PMID 38732103, 2024). "Recent studies observed increased OGT and O-GlcNAcylation level in human colon cancer tissues compared to adjacent normal tissues, indicating an essential role of OGT-mediated protein O-GlcNAcylation in the pathogenesis of colon cancer." (PMID 38168435, 2024). "In a previous work, we showed that artificially modulating O-GlcNAcylation levels in colon cancer cells, led to compensatory adjustments in OGT and OGA in an attempt to restore basal O-GlcNAcylation levels." (PMID 39426963, 2024). "Next, we use GFP agarose immunoprecipitation and liquid chromatography coupled to tandem MS (LC-MS/MS) to identify different proteins that interacted with OGT in human colonic cancer cell line HT29." (PMID 38168435, 2024). "In hepatic and colon cancer cells, pharmacological inhibition of mTOR activity by rapamycin decreases OGT expression by regulating protein stability." (PMID 33801653, 2021). "This study demonstrated that XIAP acts as an E3 ubiquitin ligase for OGT, resulting in the proteasomal degradation of OGT and the inhibition of colon cancer cell growth and invasion." (PMID 32994395, 2020). "Collectively, these results indicate that XIAP promotes the proteasomal-dependent degradation of OGT in HCT116 colon cancer cells." (PMID 32994395, 2020). "Contrary, decreasing O-GlcNAcylation levels by silencing OGT reduces proliferation, adhesion, migration and anchorage-independent cell growth of colon cancer cell lines." (PMID 33126652, 2020). "Normal O-GlcNAc-modified XIAP mediates the ubiquitin-proteasomal degradation of OGT, resulting in the inhibition of colon cancer cell growth and invasion." (PMID 32994395, 2020). "We reasoned that OGT inhibition would mimic in the tumor the presence of severe nutritional stress, and indeed, we demonstrated that nutritional stress reproduced in colon cancer cells the effects obtained with OGT inhibition." (PMID 31139149, 2019). "Increased OGT expression has been detected in numerous cancers, including bladder cancer and lung and colon cancers." (PMID 31139149, 2019). "We next investigated the effects produced by perturbation of O-GlcNAc levels on the expression of stem cell markers CD44 and CD133 by pharmacological inhibition of OGT or OGA in colon cancer cells." (PMID 31139149, 2019). "In colon cancer cells, the increased level of O-GlcNAcylation correlates with an overexpression of nucleocytoplasmic OGT." (PMID 29416702, 2018). "In that context, we studied the effect of OGT silencing in the colon cancer cell lines HT29 and HCT116 and the primary colon cell line CCD841CoN." (PMID 27252680, 2016). "Our observations indicate that OGT is crucial for the biological properties of normal colon-derived cells and colon cancer cell lines." (PMID 27252680, 2016). "Moreover, we have shown that OGT knockdown by siRNA reduced the proliferation, survival, and adhesion of colon cancer cells." (PMID 39426963, 2024).